CD4 (CD4 molecule)
Diseases named in the same sentence as CD4 in open-access papers (continued):
Sharing a sentence is not in itself a finding about the gene and the disease.
infection (continued). "Our results revealed that the CD4+ T-cell clonotypic hierarchy, set early in the response and determined by TCR avidity, can be reversed later in infection." (PMID 26728651, 2016). "For mature CD4+MHC class II+ pDC, while infection with FMDV O1 Manisa and A24 Cruzeiro increased their frequency, their expression of MHC class II significantly declined during FMDV infection." (PMID 27008425, 2016). "Prior studies also showed protection against C. muridarum challenge infection was more dependent on CD4+ vs. CD8+ T cells, and that CD4+ T cells conferred protection if C. trachomatis LGV serovars were inoculated directly into the mouse uterus." (PMID 27606424, 2016). "Thus, we speculate that the analysis of epigenetic modifications to cytokine promoters in circulating CD38+ CD4+ T cells in the context of natural or experimental infection will inform the molecular mechanisms controlling cytokine production within this cell population." (PMID 27662621, 2016). "Although immune populations emigrate normally to the genital tract following CD4+ T cell depletion in C57BL/6 mice, IFN-γ has been shown to recruit neutrophils and other cell populations to sites of infection." (PMID 27600502, 2016). "Further assessment of viral transfer during the <24 h time points, trans infection, demonstrated that BIT225 treatment resulted in lower levels of HIV-1 transfer from the MDDC to the uninfected CD4+ T cells in the three donors." (PMID 26858771, 2016). "CD4 CTL developed in response to cytomegalovirus (CMV), human immunodeficiency virus (HIV), and Epstein–Barr virus (EBV) infection in humans as well as lymphocytic choriomeningitis virus (LCMV) and mouse gammaherpes virus in mice." (PMID 27014272, 2016). "Antigen-specific PbTII CD4+ T cells (CD45.1) were transferred into wild-type CD45.2 recipients and recovered from spleens at days 2, 3 and 4 post-infection." (PMID 27176874, 2016). "We demonstrated that activation of the NF-κB pathway is critical for efficient integration of HIV in CCL19-treated resting CD4+ T cells and that the sites of HIV integration depended on the activation state of the cell at the time of infection." (PMID 27459960, 2016). "Therefore, we speculate that the abundance of eosinophils or mast cells could condition immune responses in the skin, and ultimately the development of CD4+ hyporesponsiveness in the lymph nodes draining the site of infection in mice exposed repeatedly to infective S. mansoni cercariae." (PMID 26679416, 2016). "pDCs have been shown to prime CD4 T cells and cross-prime CD8 T cells, especially in the context of infection." (PMID 27122656, 2016). "CD4 molecules and chemokine receptors are the major receptor/coreceptors used by HIV-1 for infection of target cells." (PMID 26667473, 2016). "For HIV to disseminate and seroconversion to occur, infection of activated CD4+ T-cells is critical, as activated CD4+ T-cells more efficiently produce HIV virions and transmit infection to more distant cells than do resting CD4+ T-cells." (PMID 27668294, 2016). "The predicted frequencies of Mtb-specific Effector CD4+ and CD8+ T cells in virtual active vs latent hosts separate after 300 days post infection." (PMID 27065304, 2016). "Meanwhile, the CD4+ T cells in liver showed a continuous increase in PD-1 expression (frequency and MFI) since three weeks post-infection and reached a plateau at eight weeks post-infection." (PMID 27792733, 2016). "The expression remained stable during the course of infection in CD4 T cells, while METH decreased the expression as the infection proceeded in the CD8 T cells." (PMID 27760221, 2016). "Whereas WT CD4+ T cells displayed elevated T-bet expression following infection, IRF4−/− CD4+ T cells presented with expression levels comparable to those of cells from uninfected mice." (PMID 27762344, 2016).
infection (continued). "The cellular composition of the spleens in reconstituted RAG2-/-γc-/- mice reflected the origin of the transferred cells, but also mirrored the situation found in WT or CatB-/- mice post infection, with more CD4 and less CD25+CD4+ cells." (PMID 27182703, 2016). "The difference in the level of infection obtained by SF162 (R5) and LAI (X4) can be explained by the difference in efficiency by which R5 and X4 HIV-1 viruses infect CD4+ T-cells in vitro." (PMID 26808476, 2016). "The proportion and number of CD4+ CD25+ Foxp3+ T cells was significantly higher in NK cell‐depleted mice than control mice at day 6 and 12 after infection." (PMID 27028780, 2016). "The frequency of IFN-γ+CD4+ TCRβ+ cells increased uponinfection in all depots analysed 7 days after infection, except OAT, and wasstill above controls by 21 days after infection (Figs 5eand 6e)." (PMID 27001522, 2016). "In accordance with data derived from polyclonally-stimulated CD4+ T cells, high frequencies of virus-specific IL-10+CD4+ T cells were observed in salivary glands after MCMV infection, peaking at d14 post-infection (pi)." (PMID 27926930, 2016). "Following the establishment of pre-existing by vaccination (OVA in the adjuvant TiterMax® Gold) or infection with MCMV, mice were administered CSP-coated liposomal vaccines containing the relevant OVA or MCMV core CD4+ T cell epitopes." (PMID 27861512, 2016). "Even if no cluster emerges, the top 2 principal components are dominated by Mtb-specific effector CD4+ and effector CD8+ T cells, as early as 42 days post infection, as well as Mtb-specific Central Memory CD4+ and CD8+ T cells later during infection." (PMID 27065304, 2016). "pDC-depleted mice showed significantly lower frequency and number of pulmonary CD4+CD25+Foxp3+ Treg cells than IgG-treated control mice (left and central panels) after 2 weeks of infection." (PMID 27992577, 2016). "Both CD4+ and CD8+ effector and memory T cells are shown to be essential for recovery from VZV and maintaining the latent stage of infection in the subclinical state." (PMID 27894330, 2016). "This conclusion is strengthened by cumulative data, from multiple mice at various time points throughout secondary infection (C-F); all of the responding CD8+ and CD4+ populations maintained a high, and stable, proportion of zsGreen-expressing cells." (PMID 27580079, 2016). "We also detected a strong inflammatory response in the IPS-1−/− mice leading to the opening of BBB and activation of the cell-mediated immune response with high quantity of infiltrating CD4 and CD8 T cells in later stages of infection." (PMID 26819220, 2016). "Recently, working with parasites from the New World, we reported in the murine model of infection an increase in DC populations (CD207+ and CD11c+) and in T-cells (CD4+ and CD8+) at the dermal site of L. (V.)braziliensis infection." (PMID 27073297, 2016). "Specifically, a statistically significant ~50% decrease in the levels of MHC class II expression by CD11c+ cDC, CD11c− cDC, CD4+ MHC class II+ pDC, and CD14+ monocytes was observed at 4 days post-infection, and thereafter recovered to baseline levels." (PMID 27008425, 2016). "In particular, NK‐cell depletion also enhanced the proportion of CD4+ CD25+ Foxp3+ T cells in infection sites (lung tissues) and mediastinal lymph node cells at day 6 after infection." (PMID 27028780, 2016). "BMDCs from young and aged mice were pulsed with OVA peptide followed by infection with LdWT or LdCen-/- and then co-cultured with OVA specific (DO11.10) CFSE labeled CD4+T cells." (PMID 27580076, 2016). "Despite the limited maintenance of CD4+YFP+GFP+ T cell after malaria infection, we found that the IL-10 response was amplified during secondary malaria infection compared with primary infection." (PMID 27630165, 2016).
infection (continued). "In primary infections, dendritic cells (DC) are one of the first cells infected by HIV-1 and can transfer virus to more permissive CD4+ T cells, making these cells an important target for novel antiviral therapies." (PMID 26858771, 2016). "When analyzing the expression of the selected homing molecules in the activated TEM cell subset, there was a higher percentage of CCR5, CCR2 and CD11c in the CD4+ CD44+ TEM cells at 10 and/or 14 days post-infection than in the control group." (PMID 27272720, 2016). "The concept behind the use of the CMV vectors is that infection with CMVs is benign in immunocompetent patients and results in persistent, life-long, and highly biased T cell effector memory (TEM) CD4+ and CD8+ T cell responses." (PMID 26858716, 2016). "The isolation of CD4+ T cell clones allowed determination of the HLA restriction of these new epitopes, assessment of functional avidity of the T cell clones, and investigation of whether and when the epitopes are generated during the course of natural infection." (PMID 26363059, 2015). "At 33 days post-infection, IG infected animals showed similar profiles of CD4+ and CD8+ cells to those observed in animals at 26 days of infection." (PMID 26469517, 2015). "As recent studies have shown that IL-27 mainly regulates CD4+ T cell activation during infection with intracellular pathogens, we further evaluated IFN-γ-producing CD4+ T cells in the spleen cultures using flow cytometry." (PMID 26222157, 2015). "Here, we observed that the total numbers of CD4+ T cells and CD8+ T cells in the lungs following MAp2009 infection were significantly lower at peak of the T cell response (days 8 and 10) compared to the PR8-infected group." (PMID 26381265, 2015). "LM-OVA infection led to CD44 upregulation in both CD4+ and CD8+ splenic T cells as the spleen is the primary site of infection." (PMID 26583325, 2015). "Consistent with the observation at primary infection, rA2-19F reinfection increased the frequency of IL4 expressing CD4+ T cells (15.54 ± 1.70 vs. 8.33 ± 0.82 %) and decreased the frequency of IFNγ expressing CD4+ T cells (31.46 ± 2.41 vs 48.08 ± 3.24 %)." (PMID 26231396, 2015). "Similar to mDC, monocytes were able to induce productive infection in CD4+ T-cells, as measured by total EGFP expression at day 5 post-infection." (PMID 26362311, 2015). "Hence, we hypothesizethat increased infection and depletion could affect the dynamics of early-differentiatedCD4 T cells along with other mechanisms that promote their differentiation towardsmature CD4 T cell phenotypes." (PMID 26678998, 2015). "To specifically assess the necessity of T cells, we depleted macrophages in mice that had been treated with CD4 and CD8 depleting antibodies prior to primary infection." (PMID 26182347, 2015). "CD4+ T cells from CD98hcf/f-CD4 mice secreted little IFN-γ and exhibited minimal T cell proliferation after stimulation with parasite antigens at both 10 and 70 days after infection." (PMID 26444422, 2015). "Following infection, anti-CD3 antibody treated animals showed markedly enhanced bioluminescence compared to untreated or anti-CD4 antibody treated CD8-/-JHT mice at days 7 and 9 p.i., indicating loss of control of virus replication." (PMID 25658831, 2015). "This review focuses on the relationship between CD4:CD8 ratio and clinical outcomes, inflammation, as well as ageing and HIV reservoir size in the context of treated infection." (PMID 26130226, 2015). "Because rapid entry into a target cell protects the virus from host defenses, access to CD4+ target cells at mucosal sites is likely a critical step in HIV infection, and consequently, differential access among mucosal sites may impact susceptibility to infection." (PMID 26172445, 2015). "Previously, CD4+ or CD8+ T cells with down-regulated CD62L and up-regulated CD44 expression were reported to accumulate at the site of infection." (PMID 26439698, 2015).
infection (continued). "Further, by day 4 post-infection, a dramatic increase in Tregs (CD4+CD25+) in the cecum and remains elevated through the 14-day post-infection time period." (PMID 26664962, 2015). "Infection with HIV is particularly troublesome for the immune system because it infects and destroys immune system cells called T helper lymphocytes or CD4+ T cells." (PMID 26695751, 2015). "The SIV Vpx mutant is severely attenuated in establishing new infections in inoculated rhesus monkeys, in producing high levels of virus progeny, in degrading SAMHD1 in memory CD4+ T cell in infected animals, and in inducing symptomatic disease." (PMID 25996507, 2015). "We used an acute infection assay that, in addition to the activity of soluble factors, allowed the interaction between CD8+ and CD4+ T cells either through cell-cell contacts or through the secretion of exosomes." (PMID 26551355, 2015). "The LPAC model allows for the robust infection of primary gut CD4+ T cells with CCR5-tropic HIV-1 strains, subsequently leading to CD4+ T cell depletion." (PMID 26529416, 2015). "We then compared IFNγ production by CD4+ and CD8+ T cells isolated from the lung, spleen and draining LNs of anti-IL-9-treated and isotype control antibody treated mice at day 7 post-infection." (PMID 25646821, 2015). "To distinguish between the effects of GITR on CD4 T cell accumulation versus differentiation, we transferred a 1:1 mixture of GITR+/+:GITR-/- TCR transgenic SMARTA cells one day prior to LCMV cl 13 infection." (PMID 25590581, 2015). "Cell-mediated immune responses, including CD4+, CD8+ and CD4+/CD8+ double-positive T cells, have been detected in PRRSV-infected animals, and they appear transiently from 2 to 8 weeks post-infection." (PMID 26397116, 2015). "Together, these findings identify a CD4 T cell-intrinsic role for GITR in sustaining early CD8 and late humoral responses to collectively promote control of chronic LCMV clone 13 infection." (PMID 25590581, 2015). "While proliferation of both CD4+ and CD8+ T cells peaked on day 8 post-infection, the extent of EdU incorporation was significantly higher in knockout lungs." (PMID 26709698, 2015). "Beginning on day 8 and increasing until day 55 after infection, TTR-NP mice showed high PD-1 expression on CD8+ and CD4+ T cells." (PMID 28210682, 2015). "Although the number of CD4+ and CD8+ T cells in IAV-infected lungs was comparable on day 4 post-infection, it is possible that this time point occurred prior to the initiation of the adaptive immune system." (PMID 26709698, 2015). "Likewise, miR expression analysis carried out by Bignami and colleagues in healthy CD4+ T cells exposed to gp120 in vitro, outlined that miRs profile could be not only the result of a productive infection but also of exposure to HIV products that leave a signature in immune cells." (PMID 26116514, 2015). "Our search was focused on factors contributing to CD4:CD8 T cell ratio and clinical outcome in adult HIV-positive patients in the context of treated infection." (PMID 26130226, 2015). "To evaluate the importance of CD4 T cells in this model, we depleted CD4 cells from GITR+/+ and GITR-/- mice prior to LCMV cl 13 infection." (PMID 25590581, 2015). "Over 20 years, partner notification is predicted to avert between 221 and 222 infections (IQR 140–299; 140–304) when initiating at CD4 <500 cells/μl and immediately, respectively." (PMID 26554586, 2015). "Approximately 7 h after infection, autologous violet-stained MACS-sorted CD4+ T cells were added and cultured for 4 days." (PMID 25990845, 2015). "Over 20 years, between 830 and 832 infections (IQR 530–1,127; 537–1,135) are predicted to be averted when initiating at CD4 <500 cells/μl and immediately, respectively." (PMID 26554586, 2015). "We examined the presence of CD4+ and CD8+ T cells, CD11b+ myeloid cells, and neutrophils in the lesions of L. major infected wild-type and Il22-/- mice at the peak of infection." (PMID 26285207, 2015).
infection (continued). "Further, Treg cell depletion with anti-CD25 led to increased influx of activated CD4+ and CD8+ T cells at the site of infection, enhanced Th1, Th2 and Th17 responses and reduced tissue pathology." (PMID 26512987, 2015). "Here we demonstrate that although CM is unable to protect against direct infection it does block HIV-1 capture and subsequent transfer by both Raji-DC-SIGN cells and iDCs to CD4+ T-lymphocytes." (PMID 25793526, 2015). "Twelve PHI patients with viral load (VL) <20 copies/mL, CD4 cells >500 cells/mm3, and CD4/CD8 ratio >1, on antiretroviral therapy (ART) initiated within the first 90 days of infection and continued for at least 12 months were included." (PMID 26186440, 2015). "The percentage of IFN-γ+CD3+ T cells and IL-17+CD4+ T cells in spleen, as well as the levels of IFN-γ, IL-17A/F and CCL3 in spleen and lung, significantly increased in the MAP27-immunized mice after infection." (PMID 26317210, 2015). "Compared to pre-infection levels, we found increased BST2 expression in PBMC, purified CD4+ lymphocytes and CD14+ monocytes of SIV-infected animals, which correlated with viral load." (PMID 26554913, 2015). "In order to show that human cells show enhanced expression of PD-L1 after infection with retrovirus as well, HIV infection of human CD4+ T cell was performed." (PMID 26484769, 2015). "When purified PHA/IL-2 stimulated CD4+ T-cells are infected with cell free GFP reporter viruses in vitro, infected GFP+ cells are fully visible within 2 days after infection." (PMID 26055104, 2015). "The advantage over the traditional Treg cell characterization by CD4+CD25hiCD127loFOXP3+ is that conventional CD4 T cells with an up-regulated CD25 and FOXP3 expression due to the generalized, infection-related immune activation are excluded from the analysis." (PMID 26633181, 2015). "Adoptive transfer of lower numbers of naive 1807 cells prior to infection increased the number of activated (CD44+), IL‐17 and IFN‐γ producing 1807 CD4+ T cells >20‐fold in mice infected with 2 million spores versus naïve mice." (PMID 26140582, 2015). "In contrast a regulatory response, characterized by the accumulation of CD4+CD25+Foxp3+ Treg cells was detected between days 8 and 10, and preceded by a slight suppression between days 4 and 7 post-infection." (PMID 26230099, 2015). "More recently, increased frequencies of cytolytic T cells (CTLs), CD4+CD8α+ T cells and regulatory T cells have been reported in lung tissue and bronchoalveolar lavage fluid of H1N1-infected pigs six days post infection." (PMID 25971313, 2015). "The total number of CD4+ T cells co-expressing IL-21 and IFN-γ showed a dramatic increase by day 8 post-infection, remained high at day 15 post-infection, and decreased thereafter." (PMID 25763578, 2015). "The data revealed a remarkable decrease in the percentage of CD4+CD25+ cells in the thymus from 1 to 5 dpi and in the spleen during early infection." (PMID 25803101, 2015). "With productive infection ≥106 and ≤107 PCV2 per mL blood, we observed modulation of signal module expression at the CD4+CD8interm and CD4SPs stage in the thymi of the PCV2a/b pigs (n=9)." (PMID 26038767, 2015). "Indeed, a reduction in the CD4+/CD8+ cell ratio may indicate the presence of infection." (PMID 26664411, 2015). "In these experiments, wild-type mice were infected with amastigote forms of Leishmania (L.)infantum chagasi and the presence of CD4+ and CD8+ T cells in the spleen and liver was evaluated by FACS at 30 days post-infection." (PMID 25874567, 2015). "Fifty-five days after infection, the levels of NP309–328-specific CD4+ T cells were reduced in the spleen but similar in the liver." (PMID 28210682, 2015). "Of note, CD4+/CD62L- cells expressed remarkably more CD25 on a per cell basis than CD4+/CD62L+ blood lymphocytes before and after infection with C. psittaci." (PMID 26252769, 2015).